PNMA6F (PNMA family member 6F)
Synonyms: PNMA6BL
Gene: Protein-coding gene on chromosome X (153,317,680 to 153,321,767, reverse strand). Ensembl gene ENSG00000225110.
Homologues: Orthologues: chimpanzee PNMA6F (99% identical), macaque PNMA6F (88% identical), rat Pnma6e (54% identical), mouse Pnma6e (53% identical), mouse Gm45015 (16% identical). Paralogues in human: PNMA6E (76% identical), PNMA6A (33% identical), PNMA3 (25% identical), PNMA5 (24% identical), PNMA1 (23% identical), PNMA2 (23% identical), MOAP1 (22% identical), PNMA8A (16% identical), ZCCHC18 (14% identical), ZCCHC12 (14% identical), PNMA8B (14% identical), CCDC8 (13% identical), and 1 more.